SOD2 (superoxide dismutase 2)
Diseases named in the same sentence as SOD2 in open-access papers (continued):
Sharing a sentence is not in itself a finding about the gene and the disease.
urolithiasis (4 papers, 2021 to 2023). Stone(s) within the urinary tract. "Only SOD2 polymorphism was associated with the change in the frequency of urolithiasis." (PMID 37878647, 2023). "Moreover, we verified the association of urolithiasis development and mRNA expression of IL-6, IL-8, SOD2, and NOS2 in peripheral blood mononuclear cells (PBMCs)." (PMID 37878647, 2023). "We also detected that SOD2 expression in PBMCs was lower in patients with urolithiasis than in controls." (PMID 37878647, 2023). "Analysis of mRNA expression of IL-6 (p < 0.05), IL-8 (p < 0.001), and SOD2 (p < 0.01) showed a significant decrease in mRNA level in patients with urolithiasis compared to the controls." (PMID 37878647, 2023). "Moreover, our study confirmed that patients with urolithiasis were characterised by decreased IL-6, IL-8, and SOD2 mRNA expression levels compared to the controls." (PMID 37878647, 2023). "In conclusion, our results suggest that polymorphic variants and changes in mRNA expression of IL-6, IL8, SOD2, and NOS2 may be involved in the pathophysiology of urolithiasis." (PMID 37878647, 2023). "Moreover, we have performed an additional analysis of IL-6, IL-8, SOD2, and NOS2 expression in the genotype groups of controls and patients with urolithiasis." (PMID 37878647, 2023).
Zinc deficiency (4 papers, 2013 to 2025). A deficiency of the essential metal Zinc; an essential cofactor for many enzymes. "Second, micronutrient status: Iron overload (prevalent in 32% of T2DM patients) amplifies •OH generation, while zinc deficiency (observed in 45% of T2DM cohorts) impairs SOD2 activity by reducing its cofactor availability." (PMID 41195385, 2025). "The protein levels of iNOS, SOD-2 (Mn-SOD), GPx1/2 and TrxR1 were not affected by either ethanol consumption or dietary zinc deficiency." (PMID 24155903, 2013).
abdominal aortic aneurysm (3 papers, 2018 to 2025). Enlargement and ballooning of the vessel that supplies arterial blood to the abdomen, pelvis and legs. "Firstly, although it has been shown that SOD2 can cause arterial-related diseases, there is no research to prove the relationship between abdominal aortic aneurysm and SOD2." (PMID 34777635, 2021).
acute myeloid leukemia (3 papers, 2016 to 2023). Acute myeloid leukemia (AML) is a group of neoplasms arising from precursor cells committed to the myeloid cell-line differentiation. "In fact, we recently demonstrated that the direct down-regulation of PKCe phenocopies SOD2 inhibition in acute myeloid leukemia cells and induces a marked increase in ROS." (PMID 37443826, 2023). "Moreover, in a cancer model, we demonstrated that PKCe inhibition increases ROS in acute myeloid leukemia cells, phenocopying SOD2 inhibition." (PMID 37443826, 2023).
adenoma (3 papers, 2018 to 2019). A neoplasm arising from the epithelium. "A genetic score comprising genes encoding for SOD2 (eight SNPs), CAT (11 SNPs) and GSTP1 (five SNPs), following an additive model of inheritance (0, 1 and 2 points awarded for every high-risk allele) or a SNP—adenoma risk-specific score, was explored for this purpose." (PMID 30987200, 2019).
age (3 papers, 2016 to 2023). A temporal measurement of the time period elapsed since an identifiable point in the life cycle of an organism. "Generally, valuable complementary findings were acquired in this study that the AMPK/SIRT3/SOD2 signaling pathway implicated inhibits the generation of ROS and mtROS in the case of age-related TJ function disorder in SCs." (PMID 36846717, 2023). "Looking at various studies related to the action of platelets, it has been reported that platelet mitochondrial reactive oxygen species contributes to age-related thrombosis, and endogenous superoxide dismutase 2 protects from platelet-dependent thrombin generation and thrombosis during aging." (PMID 36498873, 2022).
Anxiety (3 papers, 2013 to 2023). Intense feelings of nervousness, tension, or panic often arise in response to interpersonal stresses. "Here, we showed that SIRT3 attenuated anesthesia/surgery-induced anxiety-like behavior in mice mPFC via the ac-SOD2 K68-mediated mitochondrial oxidative stress pathway." (PMID 35372451, 2022). "We found that SIRT3 attenuated postoperative anxiety by regulating SOD2 acetylation and mitochondria-mediated oxidative stress." (PMID 35372451, 2022). "This study suggest that SIRT3 may ameliorate anesthesia/surgery-induced anxiety-like behavior by preventing SOD2 acetylation-mediated mitochondrial oxidative stress and HCN1 channel dysfunction in the mPFC of mice." (PMID 35372451, 2022). "Our results revealed that SIRT3 might have an important regulatory function in the HCN1 channel through the SOD2 acetylation-mediated mitochondrial pathway in a mouse model of postoperative anxiety." (PMID 35372451, 2022). "Therefore, the relationship of SIRT3 on SOD2 acetylation, MMP reduction, and related HCN1 channel dysfunction in postoperative anxiety-like behavior and its underlying neuroprotective mechanism were studied in this research work." (PMID 35372451, 2022). "SOD2 deletion did not lead to any anxiety‐related behaviour in any age according to the corner/center stay ratio during the open field tests (data not shown)." (PMID 37609868, 2023). "Our results suggest that SIRT3 may achieve antianxiety effects through regulation of SOD2 acetylation-mediated oxidative stress and HCN1 channels in the mPFC, further strengthening the therapeutic potential of targeting SIRT3 for anesthesia/surgery-induced anxiety-like behavior." (PMID 35372451, 2022). "Furthermore, the HCN1 channel inhibitor ZD7288 significantly protected against anesthesia/surgery-induced anxiety, but without SIRT3/ac-SOD2 expression or oxidative stress changes." (PMID 35372451, 2022).
cataract (3 papers, 2013 to 2024). Partial or complete opacity of the crystalline lens of one or both eyes that decreases visual acuity and eventually results in blindness. "H2O2-induced cataracts were linked to reduced SOD2 and CAT activities and reinforced NQO-1 activity of the lens." (PMID 35222803, 2022). "Therefore, the present study focused on quantitative relationships of SOD2, ALDH1A1, and MGST1 messenger ribonucleic acid (mRNA) levels between patients presenting with cataracts with and without PEX." (PMID 23805041, 2013).
Constipation (3 papers, 2019 to 2024). Infrequent or difficult evacuation of feces. "Furthermore, the network pharmacology analysis showed that Akt1, Stat3, Mapk8, Hsp90aa1, Cat, Alb, Icam1, Sod2, and Gsk3b can be regarded as the core anti-constipation targets." (PMID 35408632, 2022).
Dyskinesia (3 papers, 2019 to 2022). A movement disorder which consists of effects including diminished voluntary movements and the presence of involuntary movements. "CAT rs1001179 and SOD2 rs4880 were previously associated with non-motor adverse effects of dopaminergic treatment as well as with the time to occurrence of dyskinesia." (PMID 33478114, 2021). "Associations of CAT rs1001179 and SOD2 rs4880 with certain non-motor AEs of dopaminergic treatment were already detected in our previous study in the same cohort of patients, but their association with dyskinesia has never been reported before." (PMID 31156712, 2019). "We report the associations of DRD2 rs1799732, NRG1 rs3735781, CAT rs1001179, SOD2 rs4880, and SLC22A1 rs628031 with time to occurrence of dyskinesia under the univariate analysis." (PMID 31156712, 2019).
geographic atrophy (3 papers, 2014 to 2019). "Recent Genome-Wide Association Studies (GWAS) have suggested an association between a susceptible locus - rs2842992 near the SOD2 gene and geographic atrophy in AMD." (PMID 31477635, 2019). "It was reported that knockdown of Sod2 in the RPE in a mouse model of geographic atrophy (GA) leads to elevated oxidative stress, causing some of the features of GA including damage to the RPE and death of photoreceptors." (PMID 29534722, 2018).
gingivitis (3 papers, 2021 to 2025). A disorder involving inflammation of the gums; may affect surrounding and supporting structures of the teeth. "Moreover, gingival biopsies from human subjects with experimental gingivitis demonstrated an increased SOD2 expression, which declined upon resolution of the gingival inflammation." (PMID 33435582, 2021). "The reduction of oxidative stress markers, as evidenced by the downregulation of antioxidant enzymes, such as SOD2 and GSR, supports the hypothesis that SnF2 can effectively mitigate the inflammatory state associated with gingivitis and reduce oxidative stress." (PMID 41156831, 2025).
glomerulosclerosis (3 papers, 2014 to 2025). A hardening of the kidney glomerulus caused by scarring of the blood vessels. "Heterozygous Sod2 deficient mice, as compared to wild-type mice, showed ROS-induced oxidative renal damage, with massive glomerulosclerosis, tubulointerstitial damage and inflammation in the kidney." (PMID 24819633, 2014). "We suggest that endothelial LONP1, which stabilizes the SOD2 protein by protecting against SOD2 ubiquitination, exerts a protective effect on glomerulosclerosis induced by 5/6Nx and endothelial cellular injury models." (PMID 41275592, 2025). "In this study, we found that LONP1 deficiency in endothelial cells disrupted the mitochondrial redox balance and aggravated glomerulosclerosis by protecting against SOD2 ubiquitination, while LONP1 overexpression alleviated cellular inflammatory injuries." (PMID 41275592, 2025). "Therefore, we hypothesize that an interaction between LONP1 and SOD2 may play an important role in the pathogenesis of glomerulosclerosis." (PMID 41275592, 2025).
Glucose intolerance (3 papers, 2015 to 2025). Glucose intolerance (GI) can be defined as dysglycemia that comprises both prediabetes and diabetes. "Increased expression of SOD1/SOD2, together with reduced oxidative stress, was found in obese mice, suggesting to a protective effect of this enzyme against insulin resistance and induced glucose intolerance." (PMID 40428311, 2025). "Interestingly, treatment with a food supplement, including the antioxidant curcumin, rescued the levels of SOD2 and induced a decrease in body fat, glucose intolerance, and metabolic inflexibility." (PMID 40722980, 2025). "The increased oxidative burden incurred by overexpression of SOD2 in the pancreas would be predicted to cause glucose intolerance independent of changes in muscle insulin action." (PMID 25992608, 2015).
head and neck cancer (3 papers, 2017 to 2023). A primary or metastatic malignant neoplasm affecting the head and neck. "In this study, we report for the first time that HPV16 E6 and E7 oncoproteins and cigarette smoke cooperate to regulate SOD2 levels and DNA damage in head and neck cancer cells." (PMID 37108069, 2023). "A prospective and functional study is needed to provide more precise information about the role and prognostic aspect of ALDH2 and SOD2 genes in head and neck cancer." (PMID 28841898, 2017).
hypothyroidism (3 papers, 2021 to 2024). Abnormally low levels of thyroid hormone. "The genes Sod1, Sod2 and Gpx1 were reduced in tests on rats with hypothyroidism, which is similar to previous studies conducted on this species." (PMID 38338793, 2024). "Hypothyroidism increased apoptosis index, TBARS and LOOH concentrations, and reduced testicular gene expression of Sod1, Sod2 and Gpx1, as well as the expression of Grp78, Atf6, Ho1 and Chop." (PMID 38338793, 2024).
Iron deficiency (3 papers, 2022 to 2024). "Iron deficiency resulted in a lower protein expression of SOD2 (Mn-SOD) and higher SOD3 (extracellular Cu/Zn-SOD), whereas a decreasing trend in SOD1 (intracellular Cu/Zn-SOD) was observed." (PMID 35631204, 2022). "The proportions of fast-twitch fibers negatively correlated with muscle SOD-2 protein levels among all COPD patients and in the iron-deficiency group." (PMID 36986182, 2023).
iron overload (3 papers, 2011 to 2025). "Expression at the gene and protein level of CD71, transferrin receptor, was of particular interest as SOD2 deficient cells, similar to sideroblasts in patients with SA, show iron overload in the presence of an obvious defect in iron utilization." (PMID 21326867, 2011). "Mitochondrial reactive oxygen species (mROS) levels, autophagy levels and the SIRT3/SOD2 pathway were examined in the models and in the bone marrow of patients with iron overload." (PMID 33435886, 2021). "The activities of SOD2 and SIRT3 in BMMNCs from patients with iron overload were also significantly lower." (PMID 33435886, 2021).
ischemia reperfusion injury (3 papers, 2023). Adverse functional, metabolic, or structural changes in ischemic tissues resulting from the restoration of blood flow to the tissue (reperfusion), including swelling; hemorrhage; necrosis; and damage from free radicals. "Specifically, transgenic overexpression of SOD2 in the heart of DOX-treated mice improved cardiac and mitochondrial morphology, and the exercise-induced increase in SOD2 expression is associated with a cardioprotective phenotype following ischemia reperfusion injury." (PMID 37175395, 2023). "Supplementation with Ori reduced the levels of SOD2, CAT, MDA, ROS levels, and IL-1β, TNF-α in hind limb muscle tissue of ischemia–reperfusion injury mice, suggesting that Ori plays a protective role against oxidative stress and the inflammatory response." (PMID 37375489, 2023).
lupus (3 papers, 2011 to 2025). "Single-nucleotide polymorphisms of SOD2 were associated with lupus susceptibility in an Egyptian pediatric population." (PMID 39061948, 2024). "coli protein in the liver and normalized the enhanced expression of TLR-7, p-NFκB/NFκB, SOD1 and SOD2 induced by lupus." (PMID 41595543, 2025).
mastitis (3 papers, 2013 to 2021). Inflammation of breast tissue during lactation or postpartum due to an obstructed duct or infection. "SOD2 gene expression increased in mammary tissue of cows and ewes with mastitis caused by S. aureus and E. coli." (PMID 34691146, 2021). "In this study, we found the expression of SOD2 at mRNA and protein levels were up-regulated in the mammary glands of ewes with clinical mastitis compared to healthy ewes." (PMID 31159303, 2019). "Many of the genes within this category have previously been identified as being involved in the immune response to mastitis, including LBP, STAT3, S100A8 and SOD2." (PMID 23324411, 2013).
Myocardial fibrosis (3 papers, 2019 to 2025). "MiR-222-3p is known to regulate SOD2 expression in HF patients and to be involved in the inhibition of myocardial fibrosis by targeting TGFβ." (PMID 30866581, 2019). "Another study demonstrated that swimming exercise for 15 minutes per day, 5 days per week for 8 weeks inhibited myocardial fibrosis, apoptosis, and ROS production, and upregulated Sirtuins3 (SIRT3) expression and antioxidant enzyme SOD2 activity in aged MI mice." (PMID 40182630, 2025).
nasal polyps (3 papers, 2012 to 2024). "In this study, we found increased expression of both oxidases and the antioxidant enzymes SOD2 and HO-1 in nasal polyps, indicating the activation of the KEAP1/NRF2 signaling pathway in response to stress." (PMID 38756779, 2024). "The expression of NOS2, NOX1, HO-1 and SOD2 was increased in nasal epithelial cells and macrophages derived from nasal polyp tissue." (PMID 38756779, 2024). "Our results indicated that the antioxidant functions of SOD1 and SOD2 in nasal polyps are also regulated by the APA site switching of these genes." (PMID 23185289, 2012).
ovarian clear cell cancer (3 papers, 2018 to 2025). An invasive malignant neoplasm that arises from the ovary and is characterized by a predominance of clear and hobnail malignant epithelial cells. "This study confirmed the following findings: a novel therapeutic strategy for clear cell ovarian carcinomas and/or other EAOCs, in which SOD2 is strongly expressed, should be established." (PMID 30700285, 2019). "Macrophages have been shown to be infiltrated into the ovaries with PCOS, and SOD2 facilitates survival of tumor cells from oxidative stress-related death in the tumor microenvironment, including ovarian clear cell carcinoma and neuroendocrine tumors." (PMID 30596106, 2018).
prostate adenocarcinoma (3 papers, 2022 to 2025). "The GEPIA platform was used to measure the correlation between the antioxidant protein expression: Superoxide Dismutase 1 and 2 (SOD1 and SOD2) and peroxiredoxin 3 (PRDX3) with the NEK6 gene expression in prostate adenocarcinoma samples." (PMID 36672191, 2023).
psychosis (3 papers, 2017 to 2025). "Additionally, SOD2 variants have been implicated in methamphetamine-induced psychosis, likely due to overwhelmed MnSOD capacity in the presence of dopamine-derived ROS." (PMID 40725019, 2025).
renal cell carcinoma (3 papers, 2017 to 2021). "For renal cell carcinoma, SOD2 expression was negatively associated with cg18897905 and cg06346099 methylation (P < 0.05)." (PMID 31929112, 2020).
Senile plaques (3 papers, 2011 to 2025). Senile plaques are extracellular deposits of amyloid in the gray matter of the brain. "There have also been reports on the role of Mn-SOD in AD pathology; AD transgenic mouse models crossed with Sod2+/− resulted in increased accelerated behavioral deficits or senile plaques." (PMID 22332002, 2011).
synucleinopathy (3 papers, 2012 to 2025). A neurodegenerative disease that is characterized by the abnormal accumulation of aggregates of alpha-synuclein protein in neurons, nerve fibers or glial cells. "In a superoxide dismutase 2 (SOD2) transgenic mouse model, development of synucleinopathies was significantly earlier as compared to the control mouse model which proved that a compromise in the capacity to quench free radical led to enhanced fibrillation of α-synuclein." (PMID 40708841, 2025). "In a transgenic murine model ((Thy-1)-h[A30P]-α-synuclein) with SOD2 haplodeficiency, at 1 year and 4 months, exhibiting significant features of synucleinopathy compared full SOD2 control, the results indicate that an elevated level of OS could mediate the progression of PD." (PMID 32089768, 2020).
tauopathy (3 papers, 2015 to 2021). Neurodegenerative disorders involving deposition of abnormal tau protein isoforms (tau proteins) in neurons and glial cells in the brain. "Furthermore, the loss of mitochondrial proteins, such as the protease AFG3L2 and the ROS scavenger SOD2, is associated with pTau presence, indicating that mitochondrial dysfunction promotes tauopathy in the brain." (PMID 34295920, 2021).
acute pancreatitis (2 papers, 2020 to 2022). An acute inflammatory process that leads to necrosis of the pancreatic parenchyma. "The changes in the concentration and activity SOD2 in erythrocytes can result from an impaired erythropoiesis in acute pancreatitis which is associated with a slightly progressing increase in the percentage of middle-aged reticulocytes, characterized by the presence of mitochondria." (PMID 33019780, 2020). "In the plasma of patients with acute pancreatitis, a lower concentration of SOD2 was shown, compared to healthy subjects." (PMID 35205334, 2022). "This study aimed to evaluate changes in IL-6 concentration and the concentration/activity of superoxide dismutase isoenzymes (SOD1, SOD2, and SOD3) in the blood of patients with acute pancreatitis (AP) in terms of rs1800795 polymorphism in the IL6 gene." (PMID 35205334, 2022). "This study was aimed at evaluating the impact of acute pancreatitis on the changes in concentration and activity of all three superoxide dismutase isoenzymes: cytosolic SOD1, mitochondrial SOD2 and extracellular SOD3 in extracellular (plasma) and intracellular (erythrocyte lysate) compartments." (PMID 33019780, 2020).